GPR37 (G protein-coupled receptor 37)
Description:
G protein-coupled receptor that plays a role in several physiological pathways such as resolution of inflammatory pain and oligodendrocyte differentiation (By similarity). Acts as a receptor for several ligands including prosaposin, osteocalcin or neuroprotectin D1. Ligand binding induces endocytosis, followed by an ERK phosphorylation cascade. Acts as a receptor for osteocalcin (OCN) to regulate oligodendrocyte differentiation and central nervous system myelination. Mechanistically, plays a negative role in oligodendrocyte differentiation and myelination during development via activation of the ERK1/2 signaling pathway. Therefore, regulates the stability of myelin or resistance of myelin itself to demyelination. Upon activation by neuroprotectin D1 (NPD1), promotes the activation of phagocytosis in macrophages as well as the shift in cytokine release toward an anti-inflammatory profile, and thus helps to reverse inflammatory pain. In addition, the increased macrophage phagocytosis mediates protection against sepsis upon pathogen infection. Additionally, extracellular vesicles derived from efferocyte express prosaposin, which binds to macrophage GPR37 to increase expression of the efferocytosis receptor TIM4 via an ERK-AP1-dependent signaling axis, leading to increased macrophage efferocytosis efficiency and accelerated resolution of inflammation (By similarity). May also act as a maturation factor of LRP6, protecting LRP6 from the endoplasmic reticulum (ER)-associated protein degradation (ERAD) and thereby promoting the Wnt/beta-catenin signaling pathway.
Synonyms: PAELR; EDNRBL; hET(B)R-LP
Tractability: Small molecule: it belongs to a druggable protein family. Antibody: UniProt places it where antibodies can reach, with high confidence; its Gene Ontology location is reachable by antibodies, with high confidence; UniProt predicts a signal peptide or a membrane-spanning region. PROTAC: UniProt records ubiquitination sites on it.
Target class: Peptide receptor (family A GPCR); Membrane receptor; Family A G protein-coupled receptor
Gene: Protein-coding gene on chromosome 7 (124,743,885 to 124,765,792, reverse strand). Ensembl gene ENSG00000170775.
Subcellular location: Cell projection, dendrite; Synapse; Cell membrane; Endoplasmic reticulum membrane
Subcellular location (Human Protein Atlas): Nuclear membrane; Cytosol; Nucleoli
Pathways (Reactome):
Signal Transduction: G alpha (i) signalling events; Peptide ligand-binding receptors
Gene Ontology:
Molecular function: G protein-coupled peptide receptor activity; heat shock protein binding; Hsp70 protein binding; neuropeptide binding; neuropeptide receptor activity; peptide binding; prosaposin receptor activity; protein binding; ubiquitin protein ligase binding; G protein-coupled receptor activity; PDZ domain binding
Biological process: adenylate cyclase-inhibiting G protein-coupled receptor signaling pathway; neuropeptide signaling pathway; positive regulation of MAPK cascade; cellular response to reactive oxygen species; G protein-coupled receptor signaling pathway; dendrite development
Cellular component: cell surface; cytoplasm; endoplasmic reticulum; plasma membrane; receptor complex; synapse; ubiquitin ligase complex; dendrite; endoplasmic reticulum membrane; membrane
Genetic constraint (gnomAD): Loss-of-function variants: 20 observed, 43.73 expected, observed/expected ratio (o/e) 0.46, 90% interval 0.32 to 0.67. The upper end of that interval is the gene's LOEUF score, 0.67, which puts it in group 2 of 6, group 1 being the genes least tolerant of losing a copy. Missense variants: 722 observed, 816.39 expected, observed/expected ratio (o/e) 0.88, 90% interval 0.83 to 0.94. Synonymous variants: 314 observed, 329.83 expected, observed/expected ratio (o/e) 0.95, 90% interval 0.87 to 1.04.
Homologues: Orthologues: chimpanzee GPR37 (100% identical), macaque GPR37 (97% identical), rabbit GPR37 (90% identical), pig GPR37 (88% identical), guinea pig GPR37 (87% identical), rat Gpr37 (82% identical), mouse Gpr37 (81% identical), tropical clawed frog gpr37 (61% identical), zebrafish gpr37a (47% identical), zebrafish gpr37b (45% identical), Caenorhabditis elegans gnrr-5 (11% identical). Paralogues in human: GPR37L1 (34% identical), EDNRB (17% identical), EDNRA (16% identical), GRPR (15% identical), NMBR (15% identical), BRS3 (14% identical), NMUR1 (12% identical), MLNR (11% identical), GHSR (11% identical), NTSR1 (10% identical), TRHR (10% identical), GPR39 (9% identical), and 3 more.
Diseases named in the same sentence as GPR37 in open-access papers:
GPR37 is named in the same sentence as 80 diseases in open-access papers, as found by Europe PMC text mining. Sharing a sentence is not in itself a finding about the gene and the disease. The quoted sentences say what the papers report.
Parkinson disease (28 papers, 2008 to 2025). A progressive degenerative disorder of the central nervous system characterized by loss of dopamine producing neurons in the substantia nigra and the presence of Lewy bodies in the substantia nigra and locus coeruleus. "G protein-coupled receptor 37 was originally identified as a substrate of the Parkinson’s disease-related E3 ubiquitin ligase Parkin and was therefore termed parkin-associated endothelin-like receptor (Pael-R)." (PMID 40822851, 2025). "PD has been reported to bind to GPR37, which is a receptor enriched in the brain and implicated in neurodegenerative diseases, such as Parkinson’s disease." (PMID 40003957, 2025). "For instance, the orphan GPR37 which is linked to Parkinson’s disease has been reported to interact with the dopamine transporter DAT." (PMID 38495099, 2024). "A causal gene for Parkinson disease GPR37 implicates dopamine signaling in baseline refractive eye development." (PMID 34107987, 2021). "GPR37 has been implicated in the pathophysiology of Parkinson’s Disease, modulation of dopamine signaling, and Sertoli cell maturation/proliferation, but little is known about its function in the development of the nervous system." (PMID 31143101, 2019). "For examples, NRF1 target genes- PARK2, PARK6 (PINK1), PARK7, PAELR (GPR37) are associated with Parkinson’s disease." (PMID 27983596, 2016). "GPR37 has been implicated in Parkinson's disease and parkinsonism, while GPR37L1 deletion leads to precocious cerebellar development and hypertension." (PMID 26696893, 2015). "GPR37 is associated with Parkinson's disease; it associates with the dopamine transporter to modulate dopamine uptake, and it regulates behavioral responses to dopaminergic drugs." (PMID 23251443, 2012). "Deregulated GPR37-mediated G protein linked signaling pathway has been implicated in neurological disorders including Parkinson’s disease and autism spectrum disorder, as well as psychiatric diseases including bipolar disorder (BPD) and major depression disorder (MDD)." (PMID 37101222, 2023). "Its close homologue, GPR37, is implicated in Parkinson’s disease and affective disorders." (PMID 36430766, 2022). "The loss of function of GPR37 and gain-of-function of the mutated GPR37 may be a crucial molecule for Parkinson disease and ASD, respectively." (PMID 23251443, 2012). "In recent years, GPR37 has garnered increasing attention for its involvement in a variety of CNS disorders, including Parkinson’s disease, multiple sclerosis, stroke, glioma, autism spectrum disorder (ASD), and inflammatory pain." (PMID 40822851, 2025). "Translationally, the cleaved extracellular fragment Ecto-GPR37 shows promise as a fluid biomarker in Parkinson’s disease, though standardization and longitudinal validation are required." (PMID 40822851, 2025). "In cross-sectional analyses, CSF ecto-GPR37 levels correlate with motor severity and distinguish PD from healthy controls and atypical Parkinsonism." (PMID 40822851, 2025). "In Parkinson’s disease, GPR37 misprocessing contributes to ER stress and dopaminergic neurodegeneration, while in multiple sclerosis and stroke, its dysregulation alters myelin repair and neurogenic responses." (PMID 40822851, 2025). "In cellular models, overexpression of full-length GPR37 frequently leads to ER retention and activation of unfolded protein response (UPR) pathways, consistent with its role as Pael-R in Parkinson’s disease-related ER stress." (PMID 40822851, 2025). "To date, the GPR37 gene has been studied and widely described in Parkinson’s disease, in the central nervous system, and in multiple cancers and also in various mouse tissues." (PMID 33810360, 2021). "Interestingly, GPR37, also known as Parkin-associated endothelin-like receptor (Pael-R) was originally discovered through genomic library screening to find new neuropeptide receptors and is associated with neurological disorders, such as Parkinson’s disease (PD), and autism." (PMID 33981203, 2021).
Parkinson disease (continued). "(III) Overexpression of GPR37 in the nigrostriatal region of rats resulted in pathologic changes common to Parkinson’s disease." (PMID 29643766, 2018). "Both orphan GPCRs are widely expressed in the brain, where GPR37 has received the most attention for its link to Parkinson’s disease and parkinsonism, while GPR37L1 deletion leads to precocious cerebellar development and hypertension." (PMID 26635605, 2015). "GPR37 and GPRC5B are both implicated in Parkinson's disease, which has depression as one premorbid indicator, possibly concomitant with brain neurodegenerative processes." (PMID 24391664, 2013). "The four candidate genes are ubiquitin B (UBB), septin 5 (SEPT5), G protein-coupled receptor 37 (GPR37) and Tyrosine hydroxylase (TH), all of which have been involved in the Parkinson disease pathway." (PMID 21731658, 2011). "These include genes in the pathways for amyotrophic lateral sclerosis (NEF3, NEFL, NEFH), Huntington's disease (CALM3, CLTC, CLTB), neurodegenerative disorders (APLP1, NEFH, FBXW7), Parkinson's disease (GPR37) and prion disease (APLP1, NFE2L2)." (PMID 19948073, 2009). "GPR37 is a G protein-coupled transmembrane receptor with suggested roles in the brain and is related to the pathogenesis of neurological disorders, including Parkinson’s disease and autism spectrum disorders." (PMID 34903243, 2021). "Taken together, the data indicate that properly functional GPR37 may counteract aging processes and parkinsonism." (PMID 32292338, 2020). "GPR37, a parkin-associated endothelial-like receptor (PAELR), has been linked to juvenile Parkinson’s disease in humans and Parkinson disease models in mice (e.g., MPTP treated), where its absence protected against dopaminergic cell death." (PMID 31143101, 2019). "Similarly, preclinical studies show that mice lacking GPR37 are associated with deficits in motor performance and synaptic plasticity, similar to what is observed in Parkinson’s patients." (PMID 36430766, 2022). "However, work on GPR37 has been related to Parkinson’s disease." (PMID 31143101, 2019). "Moreover, GPR37 is a substrate of the Parkin enzyme, which plays a key role in Parkinson disease." (PMID 23251443, 2012). "GPR37 is a substrate of parkin (PARK2), and its insoluble aggregates accumulate in brain tissue samples of Parkinson's disease patients, AKA PaelR." (PMID 24391664, 2013). "A case study using Parkinson disease (PD) has identified four candidate genes (UBB, SEPT5, GPR37 and TH) that ranked higher than our adaptive threshold, all of which are involved in the PD pathway." (PMID 21731658, 2011).
autism spectrum disorder (9 papers, 2012 to 2025). A spectrum of developmental disorders that includes autism, and Asperger syndrome. "Mutations in GPR37 were related to the deleterious effect of autism spectrum disorder, a neurodevelopmental and neuropsychiatric disorder." (PMID 36430912, 2022). "Mutations in GPR37 are associated with autism spectrum disorders." (PMID 36430912, 2022). "In addition, GPR37 has been implicated in autism spectrum disorder, a neurodevelopmental disorder for which dysfunction of several genes associated with axonal guidance signaling pathway has been suggested." (PMID 31143101, 2019). "The gene for GPR37 is found within a locus called AUTS1, the first region of the human genome to be linked to autism spectrum disorder (ASD)." (PMID 26635605, 2015). "The GPR37 gene is located on human chromosome 7q31, a genomic region overlapping with autism susceptibility locus 1 (AUTS1), linked to neurodevelopmental disorders such as autism spectrum disorder (ASD)." (PMID 40822851, 2025). "Moreover, GPR37’s involvement in autism spectrum disorder and glioma highlights its dual role in both neural development and oncogenesis, expanding its functional landscape beyond traditional neurodegenerative contexts." (PMID 40822851, 2025). "Interestingly, a GPR37-Del321F mutation was detected in the unaffected father of an individual with autism spectrum disorder (ASD), while the GPR37-R558Q mutation was present in the affected brother and the unaffected mother." (PMID 39633709, 2024).
depression (9 papers, 2013 to 2025). "Several lines of evidence suggest that GPR37 modulates dopamine signaling, both in PD and in other dopamine-linked disorders, such as bipolar disorder and major depressive disorder." (PMID 30423289, 2019). "In our study, we found that the expression levels of GPR158 and GPR37 were significantly changed in CUMS mice with depression‐like behaviors." (PMID 40746130, 2025). "GPR37 is downregulated in the dorsolateral prefrontal cortex and anterior cingulate (brain regions associated with hedonism, impulse control, working memory and depression) in major depressive disorder (MDD) and upregulated in bipolar disorder." (PMID 35008836, 2021). "Dysregulation of GPR37 was confirmed by both qPCR and in-situ hybridization using cortical slices from a separate cohort of major depressive disorder and bipolar disorder patients." (PMID 26635605, 2015). "For example, aged female GPR37 KO mice had significantly increased anxiety and depression-like behaviors, while olfactory function was marginally improved." (PMID 26635605, 2015). "Gpr37-knockout female mice showed significantly increased anxiety and depression-like behaviors." (PMID 37101222, 2023). "Thus, while GPR37 may be downregulated in major depressive disorder, more studies are required to both confirm this result and determine the effect of bipolar disorder on GPR37 expression." (PMID 26635605, 2015). "Prosaptide is an agonist for both GPR37L1 and GPR37, yet only GPR37L1 was found in our study to be downregulated in brain regions of the depression model." (PMID 38670310, 2024). "OCN appears to regulate the expression of these receptors, suggesting that its positive effects on depression‐like behaviors may be mediated by GPR158 and GPR37, implying that these receptors could be involved in the regulation of OCN on emotion." (PMID 40746130, 2025).
Anxiety (8 papers, 2015 to 2025). Intense feelings of nervousness, tension, or panic often arise in response to interpersonal stresses. "(IV) GPR37 KO was associated with demyelination, depression, anxiety and conditioned place preference." (PMID 29643766, 2018). "Further, GPR37 deletion in mice leads to sex-dependent effects on neurotransmitter levels and anxiety." (PMID 29625592, 2018). "To determine behavioral response to the light activation of opto-GPR37, we used open field and Y-maze tests to assess their motor activity and anxiety-like behavior in response to opto-GPR37." (PMID 29643766, 2018). "Further confounding our understanding of the physiological significance of GPR37 is contradictory behavioral testing results, with some studies suggesting that GPR37 deletion increases anxiety and others show the opposite." (PMID 26635605, 2015). "Moreover, OCN/GPR37 signaling contributes to the regulation of anxiety, cognition, and neuronal plasticity, highlighting a developmental and endocrine dimension to GPR37’s functionality." (PMID 40822851, 2025). "Moreover, opto-GPR37-induced increase in the residence time in the central area of the open field chamber indicates the possible involvement of GPR37 in anxiety-like behavior." (PMID 29643766, 2018). "Besides, optogenetic activation of opto-GPR37 uncovered novel aspects of GPR37 signaling (such as IP-3 signaling) and anxiety-related behavior." (PMID 29643766, 2018). "This might suggest attenuated hypothalamic pituitary adrenal axis in GPR37KO females and might explain the protective effects of the deletion of GPR37 observed in females under ELS conditions against anxiety, given the positive association of corticosterone with anxiety." (PMID 35008836, 2021). "Thus, opto-GPR37 activation may produce the delay effect on anxiety-like behavior." (PMID 29643766, 2018). "GPR37KO females displayed less anxiety compared to GPR37KO males and WT females especially under ELS treatment condition suggesting that deletion of GPR37 might confer anxiolytic action in females." (PMID 35008836, 2021). "In response to blue light, GPR37 signaling was elicited, and subsequent biochemical (i.e., ERK phosphorylation, DARPP-32 phosphorylation, c-Fos expression) and behavioral (i.e., motor and anxiety-like) responses were assessed." (PMID 29643766, 2018). "For example, the results of the anxiety tests (EPM, light-dark box) suggest that the absence of GPR37 confers protection in females under ELS conditions." (PMID 35008836, 2021).
gastric cancer (8 papers, 2016 to 2024). A primary or metastatic malignant neoplasm involving the stomach. "Knocking down GPR37 in lung adenocarcinoma (LUAD) cells inhibited the malignant behavior, whereas elevated GPR37 in gastric cancer cells is linked to peritoneal metastases and poor prognosis." (PMID 37837549, 2023). "Aberrant expression of GPR37 was also implicated in several cancers, including gastric cancer, multiple myeloma, and hepatocellular carcinoma, yet little is known of its involvement in breast cancer." (PMID 37101222, 2023). "GPR35 is related to colorectal cancer, pancreatic cancer and stomach cancer, while GPR37 is related to glioma, melanoma and liver cancer." (PMID 37743473, 2023). "The present study shows that REG4 promotes peritoneal metastasis of gastric cancer through G-protein coupled receptor 37 (GPR37), and triggers a positive feedback loop." (PMID 27036049, 2016). "In conclusion, REG4 promotes peritoneal metastasis of gastric cancer through GPR37 and triggers a positive feedback loop." (PMID 27036049, 2016). "In the present study, we demonstrate that REG4 is able to promote peritoneal metastasis of gastric cancer through GPR37 by enhancing adhesion ability." (PMID 27036049, 2016). "Then we knocked down GPR37 in REG4 overexpressed cell lines or rhREG4 stimulated cells to test their effects upon the biological behaviors of gastric cancer cells." (PMID 27036049, 2016). "Firstly, western blot was performed to verify GPR37 expression in gastric cancer cells (data not shown)." (PMID 27036049, 2016). "Also, G protein-coupled receptor 37 (GPR37) is identified to be in the same complex of REG4, which mediates REG4′s signal transduction and promotes peritoneal metastasis of gastric cancer cell." (PMID 27036049, 2016).
autism (6 papers, 2012 to 2022). Persistent deficits in social interaction and communication and interaction as well as a markedly restricted repertoire of activity and interest as well as repetitive patterns of behavior. "GPR37, also known as parkin-associated endothelin-like receptor (Pael-R), was cloned in 1997 and was initially implicated in Parkinson’s disease (PD) as well as in autism." (PMID 36430912, 2022). "Two mutations were detected in the GPR37 gene in patients with autism." (PMID 23251443, 2012). "Here, we analyzed GPR37 in patients with autism to identify mutations related to ASD." (PMID 23251443, 2012). "We focused on GPR37, because it is localized on chromosome 7q31–33, called the AUTS1 region, to indicate the first locus linked to autism." (PMID 23251443, 2012).